BCLAF1 (BCL2 associated transcription factor 1)
Description:
Death-promoting transcriptional repressor. May be involved in cyclin-D1/CCND1 mRNA stability through the SNARP complex which associates with both the 3'end of the CCND1 gene and its mRNA.
Synonyms: Btf; KIAA0164; bK211L9.1
Tractability: PROTAC: UniProt records ubiquitination sites on it; ubiquitination databases record sites on it; its protein half-life has been measured.
Gene: Protein-coding gene on chromosome 6 (136,256,627 to 136,289,851, reverse strand). Ensembl gene ENSG00000029363.
Subcellular location: Cytoplasm; Nucleus; Nucleus speckle; Nucleus, nucleoplasm
Subcellular location (Human Protein Atlas): Nuclear speckles
Gene Ontology:
Molecular function: DNA binding; protein binding; RNA binding; transcription coregulator activity
Biological process: DNA damage response; negative regulation of DNA-templated transcription; positive regulation of apoptotic process; positive regulation of DNA-templated transcription initiation; positive regulation of intrinsic apoptotic signaling pathway; apoptotic process; mRNA stabilization; positive regulation of transcription by RNA polymerase II
Cellular component: nuclear speck; nucleoplasm; nucleus; mediator complex; cytoplasm
Genetic constraint (gnomAD): Loss-of-function variants: 10 observed, 79.56 expected, observed/expected ratio (o/e) 0.13, 90% interval 0.077 to 0.21. The synonymous counts are far from expectation, so gnomAD's model fits this gene poorly and the ratio says little. Missense variants: 609 observed, 929.77 expected, observed/expected ratio (o/e) 0.65, 90% interval 0.61 to 0.7. Synonymous variants: 248 observed, 313.22 expected, observed/expected ratio (o/e) 0.79, 90% interval 0.71 to 0.88.
Homologues: Orthologues: macaque BCLAF1 (100% identical), chimpanzee BCLAF1 (99% identical), dog BCLAF1 (98% identical), guinea pig BCLAF1 (98% identical), rabbit BCLAF1 (98% identical), mouse Bclaf1 (96% identical), rat Mtfr2 (96% identical), pig BCLAF1 (93% identical), tropical clawed frog bclaf1 (58% identical). Paralogues in human: THRAP3 (39% identical), BCLAF3 (16% identical).
Diseases named in the same sentence as BCLAF1 in open-access papers:
BCLAF1 is named in the same sentence as 56 diseases in open-access papers, as found by Europe PMC text mining. Sharing a sentence is not in itself a finding about the gene and the disease. The quoted sentences say what the papers report.
hepatocellular carcinoma (12 papers, 2019 to 2025). A malignant tumor that arises from hepatocytes. "This study explored the mechanism by which DMF regulates the mitochondrial apoptosis of human hepatoma cells through Bcl-2-associated transcription factor 1 (Bclaf1)." (PMID 39444606, 2024). "This study reveals increased BCLAF1 expression in hepatocellular carcinoma (HCC) patients, in whom elevated BCLAF1 levels are linked to escalated tumor grades and diminished survival rates." (PMID 37906282, 2023). "Curcumin induced mitochondrial apoptosis in human hepatoma cells by inhibiting Bclaf1 expression, which suggested that Bclaf1 is closely related to the development of hepatoma." (PMID 39444606, 2024). "Bclaf1 knockout resulted in increased green fluorescence, decreased red fluorescence, and decreased mitochondrial membrane potential in cells, indicating that Bclaf1 knockout induced mitochondrial apoptosis in human hepatoma cells." (PMID 39444606, 2024). "In vitro experiments demonstrated that DMF induced the mitochondrial apoptosis of human hepatoma cells through Bclaf1, thus inhibiting their proliferation." (PMID 39444606, 2024). "Immunofluorescence detection revealed that Bclaf1 was expressed in both the nucleus and cytoplasm of untreated human hepatoma cells." (PMID 39444606, 2024). "Annexin V/FITC double-staining revealed that the apoptosis rate of human hepatoma cells was increased after Bclaf1 knockout compared with the vehicle (p < 0.05)." (PMID 39444606, 2024). "This study revealed that Bclaf1 is highly expressed in human hepatoma cells and mainly distributed in the nucleus through immunofluorescence detection." (PMID 39444606, 2024). "The results illustrated that Bclaf1 overexpression depressed mitochondrial apoptosis in human hepatoma cells and that DMF induced mitochondrial apoptosis in cells by inhibiting Bclaf1." (PMID 39444606, 2024). "Flow cytometry revealed that the apoptosis rate of human hepatoma cells was decreased by Bclaf1 overexpression (P < 0.05)." (PMID 39444606, 2024). "Consistent with this view, BCLAF1 has been implicated in angiogenesis, and both BCLAF1 and SRSF10 facilitate metastasis of hepatocellular carcinoma cells." (PMID 38753413, 2024). "The mechanism by which DMF induced the mitochondrial apoptosis of human hepatoma cells through Bclaf1 was further verified in vitro and in vivo." (PMID 39444606, 2024). "Inhibition of Bclaf1 expression can induce mitochondrial apoptosis in human hepatoma cells, and the anti-tumor effect of DMF was further verified through the construction of a nude mouse transplanted tumor model." (PMID 39444606, 2024). "Subsequently, we treated mouse models with PD-L1 monoclonal antibody therapy in conjunction with BCLAF1 inhibitors to explore the prospective therapeutic effects of anti-BCLAF1 in hepatocellular carcinoma." (PMID 37906282, 2023). "BCLAF1 has been reported to promote cell proliferation and invasion in hepatocellular carcinoma, indicating an oncogenic role of BCLAF1 in cancer." (PMID 34372878, 2021). "In 2019, Bclaf1 was first reported to be involved in the occurrence and development of liver cancer, and was found to be highly expressed in human hepatocellular carcinoma Huh7 cells." (PMID 33363466, 2020). "In hepatocellular carcinoma, BCLAF1 promotes cell proliferation, invasion and 5-Fluorouracil resistance though targeting NEAT1." (PMID 33298086, 2020). "Various literatures have reported BCLAF1 roles in some carcinomas’ tumorigenesis, such as hepatocellular carcinoma and acute myeloid leukemias tumorigenesis." (PMID 33188158, 2020). "Proteomics research by the same group also found that Bclaf1 was highly expressed in human hepatocellular carcinoma tissues and compared with adjacent tissues, the difference was significant." (PMID 33363466, 2020).
hepatocellular carcinoma (continued). "After Bclaf1 knockout, Bcl-2 expression was downregulated, Bax expression was increased, and the Bcl-2/Bax ratio was decreased versus the control findings (p < 0.01), indicating that mitochondrial apoptosis was induced in human hepatoma cells after Bclaf1 knockout." (PMID 39444606, 2024). "After Bclaf1 overexpression was confirmed by Western blotting, the expression of Bcl-2, a key protein of mitochondrial apoptosis in hepatoma cells, was increased and that of Bax was decreased, and the Bcl-2/Bax ratio was increased compared with the findings in the blank control group (all p < 0.01)." (PMID 39444606, 2024). "DMF induces mitochondrial apoptosis in human hepatoma cells through Bclaf1." (PMID 39444606, 2024). "In the JC-1 fluorescence probe assay, Bclaf1 overexpression resulted in decreased green fluorescence and increased red fluorescence, indicating that the mitochondrial membrane potential of human hepatoma cells was increased." (PMID 39444606, 2024). "1C8 reprograms the SRSF10-dependent alternative splicing of BCLAF1 and SREK1 in colorectal and hepatocellular carcinoma cell lines, respectively." (PMID 38753413, 2024). "In the diethylnitrosamine (DEN)-induced primary hepatocellular carcinoma rat model, CK downregulated Bclaf1 expression, inhibited the HIF-1α-mediated glycolysis pathway, and affected the proliferation of hepatoma cells." (PMID 33363466, 2020). "In addition, ginsenoside CK significantly inhibited the binding of Bclaf1 and HIF-1α, thereby suppressing HIF-1α-mediated glycolysis in anoxic human hepatoma cells and inhibiting their proliferation." (PMID 39444606, 2024).
colon cancer (10 papers, 2017 to 2025). "Functional assays found that colon cancer cells expressing wildtype BCLAF1 injected into nude mice caused a decrease in tumor incidence and tumor formation." (PMID 33782397, 2021). "Studies have shown that alternative splicing of exon 5 of BCLAF1 produces two splice isoforms, and the longer splice isoform is prevalent in colon cancer and promotes tumor proliferation." (PMID 36713456, 2022). "Although most of the studies suggest that Bclaf1 is a tumor suppressor, a recent study reported that Bclaf1 regulates the tumorigenesis of colon cancer cells, implying that there is a potential correlation between Bclaf1 and tumor progression." (PMID 30367150, 2019). "The ability of 1C8 to impact the alternative splicing of BCLAF1 was tested in the HeLa-HIV cell line as well as in three colon cancer cell lines (Caco2, SW620 and HCT116)." (PMID 27928057, 2017). "One might suggest that the TMF1 gene expression may have a role in tumorigenesis in colon cancer due to its high correlation with the BCLAF1 gene expression." (PMID 36109686, 2023). "Bclaf1 is a tumor suppressor gene involved in T-cell activation, repairing DNA damage, and pre-mRNA splicing, with a regulatory role in colon cancer." (PMID 35893234, 2022). "Overexpression of SRSF10 promotes the development of colon cancer via regulating BCLAF1 splicing." (PMID 32600379, 2020). "Moreover, SRSF10 promotes the splicing of transcription factor BCLAF1 to facilitate the tumorigenesis of colon cancer." (PMID 32600379, 2020). "However, recent studies unearthed the dark side of Bclaf1, revealing its oncogenic features in acute myeloid leukemia and colon cancer cells." (PMID 30367150, 2019).
bladder cancer (9 papers, 2020 to 2024). "As a microRNA sponge, PVT1 actively promotes the expression of b-cells lymphoma-2-associated transcription factor 1 (BCLAF1) to sponge miR-194-5p and subsequently increases malignant phenotypes of bladder cancer cells." (PMID 33188158, 2020). "For example, NF-κB and histone methyltransferase SET and MYND domain-containing protein 3 (SMYD3) were reported to be directly involved in the transcriptional regulation of BCLAF1 in diffuse large B cell lymphoma and bladder cancer, respectively." (PMID 38340178, 2024). "BCLAF1 mutations were present across multiple tumor types; melanomas had the highest overall prevalence (14.4%), with bladder cancer (9.1%) and NSCLC (4.9%) also harboring BCLAF1 mutations." (PMID 35803911, 2022). "As an oncogene of bladder cancer cells, lncPVT1 acts as a ceRNA targeting miR-194-5p to regulate the expression level of BCLAF1, thereby promoting the proliferation, migration, and anti-apoptosis of bladder cancer cells." (PMID 35965522, 2022). "Lastly, BCLAF1 was shown to activate autophagy in bladder cancer cells, underscoring that SMYD3 plays a critical role in bladder cancer oncogenesis and autophagy activation via H3K4me2/me3-mediated regulation of BCLAF1." (PMID 33637115, 2021). "In addition, it was shown that miR-194-5p was directly involved in the transcriptional regulation of BCLAF1 by binding to BCLAF1 3'UTR, thus inhibiting its transcription or translation in acute granulocytic leukemia and bladder cancer." (PMID 38340178, 2024). "In summary, SMYD3 plays critical roles in bladder cancer oncogenesis, such as interactions with IGF-1R and AKT/mTOR in a possible feedback pathway, cell cycle and apoptotic regulation, and autophagy activation via BCLAF1 regulation." (PMID 33637115, 2021). "It is worth noting that, although the authors demonstrated that SMYD3 physically interacted with the BCLAF1 promoter, it is possible that SMYD3 may regulate bladder cancer growth via AR, because of its previously reported interaction with the receptor." (PMID 32781788, 2020).
liver cancer (7 papers, 2019 to 2024). An epithelial or non-epithelial malignant neoplasm that arises from the liver. "CK induced mitochondrial apoptosis in human liver cancer cells through Bclaf1-mediated modulation of ERK signaling." (PMID 38664638, 2024). "Although BCLAF1 has been extensively investigated in liver cancer, we identify a novel and intriguing role for this protein in liver cancer immunotherapy." (PMID 37906282, 2023). "In order to further clarify the interaction mechanism between Bclaf1 and HIF-1α, we use CRISPR/Cas9 technology to knock out Bclaf1, and detect the expression of HIF-1α in liver cancer cells after knocking out Bclaf1 under hypoxia." (PMID 33363466, 2020). "Recent studies using RNA sequencing have detected a high expression of Bclaf1 in liver cancer Huh7 cells." (PMID 33363466, 2020). "IHC experiments showed that Bclaf1 was highly expressed in human liver cancer tissues compared with adjacent normal tissues; the difference in expression was significant, and Bclaf1 was expressed in both the cytoplasm and the nucleus." (PMID 33363466, 2020). "In our previous study using iTRAQ technology, we found that Bclaf1 was highly expressed in human liver cancer tissue cells." (PMID 33363466, 2020). "Western blotting results showed that Glut1, HK2, LDHA, and PDK1 expression increased and the CCK8 assay showed that knocking out Bclaf1 promoted the reduction by CK of hypoxic liver cancer cell viability." (PMID 33363466, 2020). "This suggests that CK inhibits the expression of Bclaf1 and the binding of Bclaf1 to HIF-1α in hypoxic liver cancer cells." (PMID 33363466, 2020). "Ten human liver cancer tissues were selected for proteomics analysis, which revealed a high expression Bclaf1 protein." (PMID 33363466, 2020). "The CCK8 assay results showed that knocking out Bclaf1 enhanced the ability of CK to inhibit the viability of hypoxic liver cancer cells." (PMID 33363466, 2020). "Specifically we provide mechanistic evidence supporting the use of CK to target Bclaf1 as a potential drug for the treatment of liver cancer." (PMID 33363466, 2020). "Overall, our study showed that CK inhibits the proliferation of hypoxic liver cancer cells (Bel-7404 and Huh7) and exerts its anti-tumor function by regulating the expression of Bclaf1." (PMID 33363466, 2020). "Therefore, our study is expected to provide an experimental basis for DMF as an effective S. sorbifolia flavonoid derivative to treat liver cancer with Bclaf1 as its target and provide new ideas for the targeted therapy of liver cancer in clinical practice." (PMID 39444606, 2024). "However, our focus on the hypoxic tumor microenvironment in liver cancer has led us to believe that the influence of BCLAF1 extends beyond the regulation of HIF-1α transcription during normoxic states." (PMID 37906282, 2023). "In order to determine the role of Bclaf1 in the inhibition of liver cancer cell proliferation by CK, we knocked out Bclaf1 and found that it enhanced the ability of CK to activate HIF-1α ubiquitination and inhibit the HIF-1α-mediated glycolysis pathway to inhibit proliferation." (PMID 33363466, 2020). "We thus investigated whether CK could inhibit the expression of HIF-1α through Bclaf1 and thus affect the glycolysis pathway of liver cancer cells." (PMID 33363466, 2020). "In addition, Bclaf1 was expressed to varying degrees in several liver cancer cell types (Huh7, Bel-7404, SMMC-77721, and HepG2), with higher expression in Huh7 and Bel-7404 cells." (PMID 33363466, 2020). "This study aimed to demonstrate that ginsenoside compound K (20 (S)-ginsenoside CK; CK) downregulates Bcl-2-associated transcription factor 1 (Bclaf1), which inhibits the hypoxia-inducible factor-1α (HIF-1α)-mediated glycolysis pathway to inhibit the proliferation of liver cancer cells." (PMID 33363466, 2020).
liver cancer (continued). "However, some literature pointed out that Bclaf1 promotes the transcription of HIF-1α in hypoxic liver cancer cells through the bZIP domain, thereby increasing the transcription of downstream targeting factors of HIF-1α and promoting the proliferation of HCC cells." (PMID 33363466, 2020). "Therefore, we speculate that the inhibition of liver cancer cell proliferation by CK may involve regulation of Bclaf1, which in turn inhibits the HIF-1α-mediated glycolysis pathway." (PMID 33363466, 2020). "Our research group previously found that CK regulates Bclaf1 under hypoxia conditions to affect the HIF-1α-mediated glycolysis pathway, thus inhibiting the growth of liver cancer cells through in vitro and in vivo experiments." (PMID 38664638, 2024). "Increased Bclaf1 and HIF-1α expression promoted the ubiquitination of HIF-1α and inhibited the glycolysis pathway, thereby inhibiting the proliferation of liver cancer cells." (PMID 33363466, 2020). "In order to investigate whether CK could inhibit the expression of Bclaf1 and the binding of Bclaf1 to HIF-1α, we first observed the expression of Bclaf1 in human liver cancer tissues." (PMID 33363466, 2020). "Our study provides evidence that under hypoxic conditions CK inhibited the expression of Bclaf1 in Bel-7404 and Huh7 cells, promoted the degradation of HIF-1α ubiquitination, and inhibited the HIF-1α-mediated cellular glycolysis pathway to inhibit the proliferation of liver cancer cells in vitro." (PMID 33363466, 2020).
colorectal cancer (6 papers, 2022 to 2025). A primary or metastatic malignant neoplasm that affects the colon or rectum. "BCLAF1, involved in regulating apoptosis, is upregulated in colorectal cancer, potentially allowing cancer cells to evade cell death, facilitating tumor progression." (PMID 41411347, 2025). "Splicing factor SRSF10 was reported to be involved in the mRNA splicing of BCLAF1 in colorectal cancer." (PMID 38340178, 2024). "SRSF10 can act as a sequence-dependent splicing factor to regulate the AS of BCLAF1 and mIl1RAP to promote the growth of cancer cells in colorectal cancer and cervical cancer." (PMID 35296659, 2022). "Relative to 1C8, GPS167 more efficiently shifts BCLAF1 splicing towards the non-oncogenic BCLAF1-S variant, and is cytotoxic to colorectal cancer cell lines and organoids." (PMID 38753413, 2024). "However, the proapoptotic effect of BCLAF1 is still controversial because there is no obvious difference in apoptosis in BCLAF1-deficient mice, and BCLAF1 can promote the proliferation of colorectal cancer cells." (PMID 38495003, 2024).
myeloma (6 papers, 2015 to 2022). "BCLAF1 encodes a transcriptional repressor that interacts with several members of the BCL2 family of proteins and ectopical BCLAF1 expression induces apoptosis in various cell types or autophagic cell death in myeloma cells." (PMID 29113313, 2017). "Notably, there is evidence that BCLAF1 could serve as a strong autophagy inducer by displacing beclin-1 from BCL2 in myeloma cells." (PMID 36418457, 2022). "In multiple myeloma cells, this activation of Beclin‐1 is impeded by the presence of FLIP(L): DED‐mediated heterodimerization of procaspase‐10 and FLIP(L) results in a complex possessing proteolytic activity that cleaves the BCL2‐interacting protein Bcl‐2 associated transcription factor 1 (BCLAF1)." (PMID 32096279, 2020).
acute myeloid leukemia (5 papers, 2019 to 2026). Acute myeloid leukemia (AML) is a group of neoplasms arising from precursor cells committed to the myeloid cell-line differentiation. "According to the GRN constructed by OIPCQ, for acute myeloid leukemia, two regulators BCLAF1 and NRSF reported previously are significantly important." (PMID 33828122, 2021). "In acute myeloid leukemia (AML) cell lines, we identified two distinct, unbalanced isoforms of BCLAF1: the full-length isoform, which exhibits oncogenic properties, and the short-length isoform, which seems to act as a tumor suppressor." (PMID 41872140, 2026).